MMP2 (matrix metallopeptidase 2)
Diseases named in the same sentence as MMP2 in open-access papers (continued):
Sharing a sentence is not in itself a finding about the gene and the disease.
tumor (continued). "As reported, MMP-2 and MMP-14 (MT1-MMP) are usually overexpressed in tumor cells, which play important roles in promoting cancer cell invasion and migration." (PMID 29250984, 2018). "In summary, these results suggest that ALT-C binds to α2β1 integrin in tumor cells and inhibits MMP-9 and MMP-2, but upregulates c-Myc (mRNA level)." (PMID 29713337, 2018). "The CMT cells were positive for the epithelial marker, cytokeratin-8; tumor markers, VEGF, HER-2, MMP-2, HIF-1α, and Bcl-2; and hormone receptors, PGR and EPOR, while negative they were for estrogen receptor, ER." (PMID 30410940, 2018). "Previous reports showed that radiation enhanced MMP-2 and MMP-9 secretion and activity, which enhanced tumor aggressiveness and promoted tumor metastasis." (PMID 30359388, 2018). "The tumour tissue of a lesion, which was excised at 9 days after ASML PDAC cell implantation showed increased expression of Mmp2 and decreased expression of Ccl20 when compared to cells grown under cell culture conditions." (PMID 30603057, 2018). "Recent research showed that MMP-2 and MMP-9 were expressed in iCCA and participated in tumor invasion and metastasis." (PMID 29682557, 2018). "MMP-2 and MMP-9 are two important ECM degradation enzymes that promote tumor invasion and metastasis via breaking basement membrane structure and degrading ECM." (PMID 30479571, 2018). "The correlation between serum MMP-2 and clinical outcome is possibly due to the link between the MMP-2 level and tumor burden, such as lymph node involvement and advanced TNM stage." (PMID 29949618, 2018). "Here, we identified a novel pathway by which p27 inhibits BC cell invasion through another tumor suppressor, PHLPP2, in a MMP2-dependent manner." (PMID 29930380, 2018). "In the present study, we demonstrated that SNCG, as a secreted protein, also controlled secretion of many proteins in the tumor microenvironment, including ECM proteins such as fibronectin, vitronectin, the MMPs like MMP-2 and MMP-24." (PMID 29903032, 2018). "Plac1 appears to be responsible for upregulating the expression of MMP2 and MMP9, which degrade the extracellular matrix to promote tumor cell invasion and metastasis." (PMID 29704427, 2018). "Tumor size, serum levels of IFN-γ and IL-4 by ELISA, and Ki-67, MMP2, MMP9, VEGF and E-cadherin markers by IHC method were evaluated." (PMID 30127820, 2018). "Western blot was used to demonstrate that Plac1 regulates the PTEN/AKT signaling pathway, which further regulates MMP2 and MMP9 to promote tumor cell invasion and metastasis." (PMID 29704427, 2018). "Changes in several ECM components known to promote growth of tumour cells, such as the collagens COL1A1, COL1A2, and the MMP2 metalloprotease were also evident in XRCC1 KD cells, again reflecting an activated fibroblast phenotype." (PMID 29568385, 2018). "The combination of chemokine CXCL12 and its receptor CXCR4 can up-regulate the expressions of MMP-2 and MMP-9 in tumor cells and reduce the secretion of tissue inhibitor of metalloproteinases (TIMPs)." (PMID 29305742, 2018). "MMP-2 and MMP-9 are major proteolytic enzymes contributed to ECM degradation to promote tumor cell migration and invasion." (PMID 30359388, 2018). "Among the MMPs, MMP1, MMP2, MMP9 and MT1-MMP produced by both stromal and tumor cells degrade and migrate through the ECM." (PMID 30241395, 2018). "Matrix metalloproteinases (MMPs), especially MMP-2 and MMP-9, are responsible for the degradation of components of the basement membrane and extracellular matrix, thereby promoting tumor invasion." (PMID 29867502, 2018). "MMP-14 also has a central role in tumor invasion and not only degrades the ECM but also promotes the secretion of pro-MMP-2." (PMID 29358963, 2017). "Overall, the most important mechanisms in MM are the production of MMP-9, activation of MMP-2 and induction of MMP-1 by the neoplastic cells, since they are major players for bone resorption and tumor spreading." (PMID 28099912, 2017).
tumor (continued). "To investigate the relationship between MMP‐13 and MMP‐2 expression and tumour blood supply patterns in different stages of LCLC, we examined the expression levels of MMP‐13 and MMP‐2 and tumour blood supply patterns in different stages of LCLC." (PMID 28766880, 2017). "Suppressing HOTAIR upregulates the HOXA5 level and downregulates MMP2 and MMP9, which are critical players in tumor invasion and metastasis." (PMID 28931862, 2017). "In summary, our data demonstrated that HPßCD-HET0016 decreases MMP-2 and -9, CD44, and N-cadherin expression, migration and invasion of tumor cells and consequently reduces lung metastasis." (PMID 28609459, 2017). "We also found that the interaction of tumor cells with monocytes promoted high levels of matrix metalloproteinases (MMP)-1, MMP-2, and MMP-10." (PMID 28337194, 2017). "MMP2 and MMP9 belong to MMP family, which have important roles in tumor cell invasion and metastasis." (PMID 28388883, 2017). "RERG increased the expression of TIMP-2 and inhibited the expression of MMP-2 and MMP-9, providing support for a mechanistic explanation of the inhibition of tumor microvessel growth and size by RERG." (PMID 28659184, 2017). "We found that all GBM cells expressed the tumor marker GFAP, and some expressed MMP-2 and TIMP-1 both in their cytoplasm and membrane." (PMID 28234925, 2017). "Specifically, TANs secrete MMP2, oncostatin M, and hepatocyte growth factor (HGF), which remodel ECM and subsequently induce tumor invasion and metastasis." (PMID 27965469, 2017). "MMP-2 and MMP-9, are potent gelatinases and have been correlated with the processes of tumor cell invasion and metastasis, play an important role in the various pathologies such as development and progression of cancer." (PMID 28522860, 2017). "COX-2 promotes the secretion and release of MMP-2 and MMP-9 to involve in tumor progression and metastasis." (PMID 28938623, 2017). "Previous study showed that upregulated MMP-2/9 contribute to cells migration and invasion abilities through STAT3-dependent signaling pathway in tumor cells." (PMID 29383152, 2017). "The interaction of MMP2 and CD44 is an important factor in selectively regulating the tumor microenvironment to promote tumor cell metastasis and is considered to be an inducer of EMT." (PMID 28679402, 2017). "Matrix metalloproteinases (MMPs), MMP2 and MMP9 in particular, have been regarded as major molecules that assist tumor cells by cleaving several ECM components and it paves the way for detachment and dissemination during metastasis." (PMID 29219852, 2017). "The expressions of CXCR7, MMP‐2, VEGF and CD31, the indexes of tumour metastasis, were determined by immunohistochemical analysis of tumour tissues." (PMID 28429395, 2017). "Further, it seems that P70s6k, MMP2, and BCL-xL are downstream molecules of RhoC that are closely involved in the formation, metastasis and apoptosis of tumor cells." (PMID 28818073, 2017). "Western blot analysis revealed that MMP2 and MMP9, two metalloproteinases which play critical roles in tumor invasion and migration, were also reduced after CCDC109B knockdown." (PMID 28754121, 2017). "Our previous findings showed that BDM is a potent matrix metalloproteinase (MMP) inhibitor, especially the gelatinases (MMP‐2 and MMP‐9), that play important roles in tumor invasion, metastasis, and angiogenesis." (PMID 28211615, 2017). "In the border zone between central tumor and tumor periphery as well as in the tumor periphery, MMP-2 was diffusely expressed, but some tumor cells with intense MMP-2 expression were observed." (PMID 28234925, 2017). "Both the MAPK and AKT pathways are broadly reported to directly or indirectly regulate MMP-2 and MMP-9, as well as tumour migration and invasion." (PMID 28729634, 2017). "Inhibition of sorcin expression can down- regulate the expression of CTSZ, MMP2, MMP9 and p-STAT3 followed by suppression of tumor growth and metastasis." (PMID 29262638, 2017).
tumor (continued). "We also analyzed the levels of vimentin and matrix metalloproteinase-2 (MMP-2), levels of which are known to increase in EMT-undergoing cells and promote tumor invasion." (PMID 28193222, 2017). "To verify the regulation of TIMP2 by EZH2, we performed loss- and gain-of-function experiments of EZH2 and examined TIMP2 expression, MMP2 and MMP9 expression and proteolytic activity, and tumor cell migration and invasion." (PMID 28620234, 2017). "As MMP2 and MMP9 facilitates the detachment of tumor cells from primary tumor site and VEGF promotes dissemination via ERK2 and Ras, TIMP1 is directly involved in inhibition of MMP's and halt metastatic process." (PMID 29219852, 2017). "CXCR7‐shRNA can also suppress tumour invasion and metastasis to improve the efficacy of TACE for HCC treatment by reducing the expressions of CXCR7, MMP‐2 and VEGF." (PMID 28429395, 2017). "In the present study we investigated the immunohistochemical expression of MMP-2 in 89 astrocytic brain tumors and found that MMP-2 was expressed by tumor cells and blood vessels." (PMID 28234925, 2017). "In this study, we observed that the levels of MMP-1, MMP-2, and MMP-10 significantly increased in co-cultures of tumor cells/monocytes, and we have previously shown that this correlates with increased collagen degradation." (PMID 28337194, 2017). "We then confirmed pro-angiogenic cytokines (IL8 and IL6), TIMP-2, and MMPs (MMP-2 and MMP-9) in the isolated tumor tissues by IHC." (PMID 28659184, 2017). "We observed that sunitinib-resistant LL/2 cancer cells exhibited increased migration and invasion in vitro, and enhanced metastatic potential in vivo, companied by MMP2 and MMP9 overexpression, which play crucial roles in tumor invasion and metastasis." (PMID 28978115, 2017). "From a mechanistic perspective, MMP2, MMP12 and VEGFA, which are produced by macrophages and are important in tumor invasion and angiogenesis, are downregulated upon blockade of the CSF1/ CSF1R axis." (PMID 28467800, 2017). "Indeed, a tumour-suppressive role for miR-130b in PCa has been proposed (although the mechanism underlying its downregulation was not disclosed), counteracting metastasis formation through MMP2 downregulation." (PMID 28166834, 2017). "Studies have shown that MMPs, particularly MMP-2 and MMP-9, play a role in tumor angiogenesis, invasion, and metastases." (PMID 29138529, 2017). "MMP2, MMP9 and FN1 (Fibronectin 1) play important roles in tumor metastasis and are closely correlated with the migration and invasion of tumor cells." (PMID 29100277, 2017). "Immunohistochemistry was performed to detect the expressions of CXCR7, MMP‐2, vascular endothelial growth factor (VEGF) and intratumoral CD31‐positive vessel count in tumour tissues of mice." (PMID 28429395, 2017). "MMP2, MMP9, and MMP13 are the main members of the MMPs family and had been reported to play a key role in tumor migration and remote metastasis in HCC and other cancers." (PMID 28959024, 2017). "Matrix metalloproteinases (MMPs), a family of zinc-binding proteins including MMP2 and MMP7, have been shown to play a central role in tumor cell invasion and metastasis due to their ability to degrade the extracellular matrix." (PMID 28968424, 2017). "Celecoxib treatment also decreased the expression levels of Wnt pathway components and target genes, such as β-catenin, p-GSK-3β, MMP-2, Survivin, AXIN2, CYCLIN-D1 and C-MYC, and the CSC marker SOX-2 in the xenograft tumor tissues." (PMID 29383157, 2017). "Matrix metalloproteinases (MMPs) including MMP-2, MMP-7, and MMP-9 are known to promote tumor progression and cancer stemness." (PMID 29340100, 2017). "As expected, we also observed tumor‐promoting factors (TGFβ, VEGF, MMP‐2, MMP‐9, and HIF‐1α) were reduced in BDM‐treated groups compared with the control animals." (PMID 28211615, 2017).
tumor (continued). "Using primers specific for human gene transcripts, the relative gene expression was determined in the tumor, and by using mouse-specific primers, contribution from the stromal cells was analyzed for TGF-β1, MMP-9 and MMP-2." (PMID 28819116, 2017). "Both in vivo and in vitro treatment of AGEs accelerate the tumor invasion and metastasis, with upregualtion of RAGE, Specificity Protein 1 (Sp1), and MMP2 protein expression, as well as enhancement of MMP2 activity." (PMID 29262634, 2017). "MMP-1, MMP-2 and MMP-9 were all increased in tumor samples compared with matched, corresponding normal tissues." (PMID 28915603, 2017). "These evidences indicated different roles and different demands of MMP-2 and MMP-9 expression among tumor growth stages." (PMID 28606135, 2017). "PA also significantly suppressed the induction of cell invasion and motility induced by 12-O-tetradecanoylphorbol-13-acetate (TPA, a tumor promoter) through inactivation of ERK1/2 signaling, downregulation of MMP-2, and upregulation of TIMP-2 in HeLa cells." (PMID 29267213, 2017). "MMP-2 and MMP-9 are the most widely studied and reported, with evidence for key roles in angiogenesis, tumor growth and extracellular matrix remodeling." (PMID 28241871, 2017). "TGF-β acted as a tumour promoter in advanced stages of CRC, which potentially led to increased expression of MMP-2 and COX-2." (PMID 28376764, 2017). "The expression of MMP-2 and MMP-9 were both higher in LL/2-R than LL/2-P cells, also higher in tumor tissues from LL/2-R than LL/2-P in mouse models." (PMID 28978115, 2017). "In invasive tumor cells, two MMPs, MMP-2 and MMP-9, are predominantly upregulated and take crucial roles in invasion and metastatic spread of tumor." (PMID 29234420, 2017). "Collected the tumor tissues were subjected to western blot showed decreased protein expression of pSTAT3 ser727, total STAT3, Bcl-2, Bcl-XL, FAS, cyclin D2, MMP2, and MMP9 in metformin treated vs. control mice." (PMID 28114390, 2017). "MMP-2 and MMP-9 are known to degrade the BM and ECM, and this degradation facilitates migration and invasion of tumor cells." (PMID 29157266, 2017). "Based on the immunohistochemical staining results, compared with the untreated doxycycline groups, E-cadherin and α-SMA exhibited high expression levels, whereas vimentin, MMP2 and MMP9 exhibited low expression in tumor tissue." (PMID 28187433, 2017). "CXCR7‐shRNA inhibits tumour invasion and metastasis to improve the efficacy of TACE in HCC by reducing the expressions of CXCR7, MMP‐2 and VEGF." (PMID 28429395, 2017). "We observed constitutively elevated levels of cytokines MCP-1, G-CSF, and RANTES in tumor cells, and of IL-1β, IL-8, MMP-1, MMP-2, and MMP-10 after co-culture." (PMID 28337194, 2017). "MMP-2 and MMP-9 of the MMP family have been thought to play important roles in the processes of tumor invasion and metastasis." (PMID 29280977, 2017). "Accumulating evidences also showed that DDR1 functioned as an inducer of MMP2 and MMP9, which contributed to matrix components degradation during tumor invasion." (PMID 28743276, 2017). "Since MMP2, MMP7 and MMP9 are important for the degradation of the tumor matrix, we investigated their protein levels by Western blot and the activity of MMPs by zymography." (PMID 28250971, 2017). "MMP-2 and MMP-9 can specifically degrade the type IV collagen which is the dominant component in ECM, facilitating tumor cell migration and metastasis." (PMID 29050226, 2017). "MMP-2/-9 are extracellular enzymes that promote ECM degradation and promote the movement of tumor cells." (PMID 28767067, 2017). "In contrast, MMP2, MMP9, and Cyclin D1 levels were decreased in tumour tissues with downregulated CEP55 expression." (PMID 28724890, 2017).
tumor (continued). "This vascularization facilitates the metastatic process, promoting the migration/circulation of tumor cells, thanks to matrix degradation by matrix metalloproteinases (MMP2, MMP7 and MMP9), which are released by tumor cells and by TAMs as well." (PMID 27823976, 2016). "As MMPs, particularly MMP-2 and MMP-9, are necessary for tumor angiogenesis and Activin A has been characterized as a potent inhibitor of this process, we next examined the effect of Activin A overexpressing cultures on endothelial tube formation." (PMID 27829391, 2016). "As expected, we found that gene expression patterns are different in PC tumor samples compared to normal, undiseased peritoneum with a number of genes differentially regulated: BAG1, CCNB1, CD44, CLDN4 and 6, MMP2, MKI67, MUC1, MYBL2, and SERPINB3." (PMID 27542596, 2016). "MMP-2 inhibition in tumor cells was also found to decrease MSC migration through the inhibition of SDF1/CXCR4 signaling, which indicates a mediatory effect for MMP-2 in the migration of MSCs." (PMID 27612636, 2016). "MMP-2 and MMP-9 are collagenases which favor tumor growth and invasion by digesting the extracellular matrix surrounding the tumor tissue." (PMID 26911838, 2016). "A mechanistic study showed that the activities of MMP-2 and MMP-9 in tumor cells were decreased by treatment with zingerone." (PMID 27323807, 2016). "Here, we found that embelin decreased angiogenesis and MMP2 expression within tumor tissues at late carcinoma stage, suggesting that attenuation of M2 polarization of TAMs may partially contribute to the inhibition of tumor progression by embelin as our previously reported." (PMID 26799669, 2016). "Previous studies have shown that S100A4 expression can upregulate the matrix metalloproteinases (MMPs), which play critical role in tumor metastasis through degradation of extracellular matrix (ECM), including MMP-9, MMP-13, and MMP-2." (PMID 26903691, 2016). "Increased activity of MMP2 and MMP9 seems to play a key role in the growth and invasion of tumor and its metastasis." (PMID 27110571, 2016). "MMP2 and MMP9 are belonging to matrix metalloproteinases family, which are vital in tumor invasion and heterogeneous adhesion." (PMID 27120794, 2016). "Our results suggest that zingerone possesses antiangiogenic activity by inhibiting the activities of MMP-2 and MMP-9 under hypoxic conditions during tumor progression." (PMID 27323807, 2016). "MMP2 and MMP9 are secreted into the extracellular space, but they can also become localized at the surface of tumor cells." (PMID 27042827, 2016). "Our results demonstrate that MMP-2, MMP-7, and MMP-9 expressions correlate with various morphological features of the PDAC tumor such as inflammation, necrosis, and formation of the new blood vessels." (PMID 27429508, 2016). "As downstream effectors of the Wnt/β-catenin pathway, c-myc, CyclinD1, MMP-2, and MMP-7 promote tumor cell proliferation, cell cycle, and migration." (PMID 27533254, 2016). "Meanwhile our study showed that overexpression of HIF-2α enhanced the expression of MMP2 and MMP9, which are closely related to tumor metastasis, are also significant to EMT." (PMID 26842802, 2016). "MMP14 can cleave a variety of substrates, including cell surface proteins (such as CD44) and other MMPs (such as pro-MMP2 and pro-MMP13), and induce ECM degradation and tumor cell invasion by increasing the secretion of other MMPs." (PMID 27564100, 2016). "Given the importance of matrix metalloproteinases (MMPs) in tumor metastasis, we also tested the ectopic expression of PAX3 on the expression of MMP-2, –9 and –14 in BCPAP, 8305C and FTC133 cells." (PMID 27458157, 2016). "Using both in vitro and in vivo models, we demonstrate that Rab40b and its effector protein Tks5, regulates MMP2 and MMP9 targeting and secretion during cell invasion and tumor growth." (PMID 27789576, 2016).